TRPM7 (transient receptor potential cation channel subfamily M member 7)
Diseases named in the same sentence as TRPM7 in open-access papers (continued):
Sharing a sentence is not in itself a finding about the gene and the disease.
glioma (continued). "We found FOSL1 levels were positively correlated with the glioma grades in a total of 75 glioma patients and correlated to the established GSC markers ALDH1 and TRPM7, suggesting FOSL1 is a diagnostic marker and potential therapeutic target for glioma patients." (PMID 37642779, 2023). "In terms of different grades of glioma, cytoplasmic staining of TRPM7 was significantly increased in grade IV GBM compared with that in grade II glioma (p < 0.05), while nuclear staining of TRPM7 was significantly increased in grade IV GBM compared wth that of grade II gliomas (p < 0.05)." (PMID 37642779, 2023). "We previously reported that TRPM7 regulates glioma cells’ stemness through STAT3." (PMID 37642779, 2023). "TRPM7 and TRPM8 have both been linked to glioma proliferation." (PMID 36768856, 2023). "We found that the expression of TRPM7, ALDH1, and FOSL1 protein is associated with grades of malignant glioma, and TRPM7 protein expression correlates to the expression of ALDH1 and FOSL1 in glioma patients." (PMID 37642779, 2023). "As FOSL1 is a key glioma regulator, it is expected that other TRPM7-mediated FOSL1 activations could contribute to glioma pathogenesis, other than HOTAIR and miR-301a-3p." (PMID 36844925, 2022). "TRPM7-mediated HOTAIR overexpression promoted glioma cell proliferation and invasion." (PMID 36844925, 2022). "MGR2 glioma cells also express TRPM7 and display TRPM7 currents." (PMID 34458247, 2021). "Finally, targeting Notch1 effectively suppressed TRPM7-induced growth and proliferation of glioma cells through cell G1/S arrest and apoptotic induction." (PMID 33381038, 2020). "Next, we determined whether TRPM7 silencing by siRNA TRPM7 (siTRPM7) induces cell growth arrest or apoptosis to reduce glioma cell proliferation using cell cycle analysis and annexin V staining assay." (PMID 33381038, 2020). "To determine whether or not our previous findings are not only limited to A172 cells, we tested the number of CD133 + cells in response to changes in TRPM7 expressions in additional glioma cell (GC) lines." (PMID 33381038, 2020). "Therefore, our results show that TRPM7 regulates Notch signaling consistently through Notch1 signaling in glioma tumorigenesis." (PMID 33381038, 2020). "Our previous studies revealed that TRPM7 plays a vital role in glioma cell proliferation." (PMID 33381038, 2020). "Results show that the percentage of apoptotic glioma cells increased from (17.59 + 5.32) to (19.16 + 6.4)% in the controls compared to those silenced by Notch1; and (14.29 + 3.15) to (18.87 + 5.57)% in TRPM7-wt transfected A172 cells compared to those co-transfected with TRPM7 and siNotch1." (PMID 33381038, 2020). "TRPM7 knockdown-induced suppression of the growth and proliferation of glioma cells could be through G1/S arrest and the inhibition of the tumor cell entry into S and G2/M phase." (PMID 33381038, 2020). "To further determine the difference in TRPM7 and Notch1 expression in glioma cells grown in monolayer and glioma neurospheres, we compared those indexes between glioma cells grown in monolayer and GSC spheres derived glioma cells by performing Western blot analysis." (PMID 33381038, 2020). "To further explore whether or not TRPM7 can be a potential drug target in malignant glioma, we analyzed TRPM7 expression in publicly available glioma microarray studies using the Oncomine database and gene microarray data analysis tool." (PMID 33381038, 2020). "Therefore, our results indicate that TRPM7 regulates the Notch1 pathway in all glioma cell lines even though gliomas are highly heterogeneous with variation in biological characteristics among different glioma cell lines." (PMID 33381038, 2020). "Taken together, the discovery of cellular and molecular targets modulated by the tumor suppressor miR-28-5p and its upstream regulator TRPM7 molecule provides key insights into the potential mechanisms of glioma tumorigenesis and suggests novel therapeutic targets for glioma treatments." (PMID 31921670, 2019).
glioma (continued). "TRPM7 is frequently overexpressed in malignant cells as well as in our glioma cell lines." (PMID 28410232, 2017). "For instance, mRNA encoding TRPC1, TRPC6, TRPM7, TRPM8, TRPV4, and TRPML2 appeared up-regulated in GBM tumor specimens in comparison with normal tissues and their expression was found to increase with glioma tumor grade with the highest mRNA level found in GBM patient samples." (PMID 33928077, 2021). "To further investigate the underlying mechanism in glioma cells with TRPM7 knockdown by TRPM7 siRNA that undergoes a failure of growth, we determined if the apoptotic process is involved in GBM cells when treated with TRPM7 siRNA and employed in an apoptosis assay." (PMID 33381038, 2020). "In the current study, we further investigated whether or not changes in glioma cell proliferation and migration might be caused by channel domain-mediated and/or kinase domain-mediated TRPM7 activation." (PMID 31921670, 2019). "Therefore, we chose miR-28-5p to further elucidate the TRPM7-mediated pathways in glioma." (PMID 31921670, 2019). "However, it does not exclude the possibility that other signal pathways like JAK/STAT pathway might also be involved in TRPM7-mediated astrocyte proliferation, just as TRPM7 channel regulates glioma stem cells through STAT3 and Notch signaling pathways." (PMID 25799367, 2015). "Further evidence has been provided for the role of ion channel TRPM7 in GBM invasion, whereby inhibition or knockdown of TRPM7 reduces human glioma cell migration and invasion." (PMID 40527011, 2025). "More recently, a detailed analysis has revealed that in TRPM7-mediated Notch1 signaling, the expression of CD133 and ALDH1 are crucial in glioma cell proliferation and glioma stem cell stemness." (PMID 38255793, 2024). "Based on our previous findings that TRPM7 enhances glioma stemness by triggering STAT3 activation, in the present study, we will investigate the mechanisms by which TRPM7/STAT3/FOSL1 regulatory axis drives stemness and growth in glioma." (PMID 37642779, 2023). "In studies using the human glioma cell lines, we found that FOSL1 mRNA and protein accumulate upon upregulation of TRPM7." (PMID 37642779, 2023). "There is a growing consensus that TRPV1, TRPV2, TRPM2, TRPM3, and TRML1 exert anti-tumorigenic properties in glioma, while TRPC1, TRPC6, TRPM7, TRPM8, and TRPML2 promote glioma growth and proliferation." (PMID 36768856, 2023). "These combined results demonstrated that TRPM7 induced FOSL1 transcriptional activation, which is mediated by the action of STAT3, a mechanism shown to be important in glioma stemness." (PMID 37642779, 2023). "The protein expression of TRPM7 and GSC markers ALDH1 and FOSL1 were then examined by IHC in glioma brain TMA obtained from glioma patients at BioCoreUSA." (PMID 37642779, 2023). "We previously demonstrated that FOSL1 is a response gene for TRPM7 and downregulation of FOSL1 can hinder glioma proliferation and invasion." (PMID 37642779, 2023). "One of our findings shows that TRPM7 activates JAK2/STAT3 signaling pathways and leads to increased glioma cell proliferation and migration/invasion." (PMID 37642779, 2023). "Several TRP channels have been studied as potential biological markers of glioma progression and prognosis, including TRPC1, TRPC6, TRPM2, TRPM3, TRPM7, TRPM8, TRPV1/2." (PMID 36768856, 2023). "In the current study, we found a new pathway that TRPM7 transactivates the FOSL1 gene through transcription factor STAT3 and enhances glioma stemness." (PMID 37642779, 2023). "The gene expression levels of TRPC1, TRPC3, and TRPC5 were significantly higher in low-grade glioma (LGG), while the levels of TRPC4, TRPC6, TRPM7, MCOLN1, MCOLN2, and MCOLN3 were significantly higher in high-grade glioma (HGG)." (PMID 35625048, 2022). "As expected, TRPM7 and Notch1 are highly correlated with the GSC markers CD133 and ALDH1 in GSC spheres compared to that in the glioma monolayer cells." (PMID 33381038, 2020).
glioma (continued). "In summary, TRPM7 is responsible for sustained Notch1 signaling activation, enhanced expression of GSC markers, and regulation of glioma stemness, all of which contribute to malignant glioma cell growth and invasion." (PMID 33381038, 2020). "TRPM7 is responsible for sustained Notch1 signaling activation, enhanced expression of GSC markers CD133 and ALDH1, and regulation of glioma stemness, which contributes to malignant glioma cell growth and invasion." (PMID 33381038, 2020). "As shown by the Western blot, all glioma cell lines A172, U87MG, U373MG, SF767, and SNB19, as well as two cell lines resistant to TMZ, T98G, and LN18, express an almost equal amount of TRPM7 with U87MG and SNB19 having slightly lower levels of expression." (PMID 33381038, 2020). "Our data show that TRPM7 expression highly correlates with the expression of CD133 and ALDH1 in both bulk glioma cells and in GSCs, which indicates that TRPM7 is very important in GSC formation." (PMID 33381038, 2020). "We have reported that TRPM7 channels, a subfamily member of the transient receptor potential (TRP), regulate glioma stem cell (GSC) growth/proliferation through STAT3 and Notch signaling pathways." (PMID 31921670, 2019). "In addition, we demonstrated that FOSL1 is a response gene for TRPM7, and the FOSL1 gene serves as an oncogene to promote glioma proliferation and invasion." (PMID 37642779, 2023). "Among them, TRPM2 and TRPM3 would exert anti-tumorigenic effects, while TRPM7 and TRPM8 may contribute to glioma malignancy." (PMID 33928077, 2021). "In the current study, we further determined the specific component of Notch signaling that is critical in response to altered TRPM7 expression and results in the expression of GSC markers and treatment failure of current chemo- and radiotherapies against glioma." (PMID 33381038, 2020). "Considering both TRPM7 and Notch signaling function as oncogenes in glioma formation, it is not surprising to see that U87MG cells, transfected with M7-wt, express increased levels of Notch1 NICD, Notch2 NICD, and Notch3 NICD." (PMID 33381038, 2020). "In addition, we previously reported that TRPM7 enhances GSC stemness by regulating the established GSC marker ALDH1 and promotes the induction of ALDH1 activity in glioma cells; therefore, we further tested the relationship between FOSL1 and GSC stemness markers TRPM7 and ALDH1 by IHC assay." (PMID 37642779, 2023). "To further gain insight into the mechanism by which TRPM7 activates transcription of the FOSL1 gene to contribute to glioma stemness, we constructed a FOSL1 promoter and its GAS mutants followed by luciferase reporter assays and ChIP-qPCR in a glioma cell line and glioma patient-derived xenoline." (PMID 37642779, 2023). "In addition, TRPM7 knockout in A172 glioma cells induced the regulation of a series of lncRNAs, of which HOX transcript antisense intergenic RNA (HOTAIR) was the most positively affected by TRPM7 depletion." (PMID 36844925, 2022). "We, therefore, determined whether or not silencing of TRPM7-mediated apoptosis in glioma cell lines can be phenocopied to the PDX model." (PMID 33381038, 2020). "At the protein levels, we first determined whether or not TRPM7 protein is expressed in these glioma cell lines." (PMID 33381038, 2020).
pancreatic cancer (25 papers, 2012 to 2025). "The control of the Hsp90α/urokinase/matrix metalloproteinase (MMP)-2 proteolytic axis was proposed as an underlying mechanism in the TRPM7-induced potentiation of pancreatic cancer cell invasion." (PMID 38255793, 2024). "Elevated TRPM7 expression in human breast and pancreatic cancer tissues has been implicated in advanced tumor grade, proliferation, and poor survival rates." (PMID 35771152, 2022). "One study showed that the deficiency of TRPM7 in human pancreatic cancer cells resulted in impaired proliferation and arrested the G0/G1 phases of the cell cycle by regulating Mg2+-sensitive suppressors of cytokine signaling 3a pathway." (PMID 32168794, 2020). "In this study, we present evidence that shRNA-mediated silencing of TRPM7 impairs the ability of pancreatic cancer cells to invade through tumor-associated extracellular matrix in response to 3% or 10% FBS." (PMID 25770184, 2015). "Further studies are indicated to help establish the functional roles of TRPM7 channels and the associated mechanisms in the growth and progression of pancreatic neoplasm." (PMID 25770184, 2015). "Taken together, these results strongly suggest that aberrantly over-expressed TRPM7 is associated with pancreatic tumor growth and possibly metastasis." (PMID 25770184, 2015). "Consistent with the findings in zebrafish TRPM7 mutants and in agreement with the role of TRPM7 as a transporter or divalent cations, addition of extra Mg2+ in the culture medium rescues the proliferative defect of TRPM7-deficient pancreatic cancer cells." (PMID 24278689, 2012). "The role of TRPM7 in the regulation of pancreatic cancer cells proliferation was also connected to Mg2+, as supplementation of the culture medium with Mg2+ reversed the decrease in proliferation caused by the knockdown of TRPM7." (PMID 32182937, 2020). "Furthermore, high TRPM7 staining in pancreatic ductal adenocarcinoma has been associated with higher TRPM7 protein staining in the lymph nodes, suggesting that TRPM7 might be involved in invasion of pancreatic cancer cells." (PMID 32182937, 2020). "Taken together, our results showed that the TRPM7 kinase domain is required for tumor growth and pancreatic cancer cell dissemination." (PMID 40274768, 2025). "We previously showed that TRPM7 silencing decreased both pancreatic cancer cell migration and invasion." (PMID 40274768, 2025). "Our recent data showed that TRPM7 interacts with the serine/threonine-protein kinase PAK1 in PANC-1 pancreatic cancer cell line by using co-immunoprecipitation and PLA experiments." (PMID 41395111, 2025). "TRPM7 has been suggested to increase cell migration through a Mg2+-dependent mechanism in human pancreatic cancer cells." (PMID 38255793, 2024). "To assess the role of TRPM7 in PS-1 cells, we used a siRNA strategy to selectively inhibit TRPM7 expression, as previously carried out in human pancreatic cancer cells." (PMID 35883700, 2022). "Aberrant TRPM7 expression in human breast and pancreatic cancers is closely correlated with clinicopathological parameters, such as tumour grade, Ki‐67 proliferation index and patient survival time." (PMID 33617107, 2021). "The study of this channel in pancreatic cancer started in zebrafish with a report stating that TRPM7 is functionally required for pancreatic epithelial proliferation." (PMID 33925979, 2021). "TRPM7 overexpression in cancer was shown mainly in breast cancer but also in prostate and pancreatic cancer." (PMID 32887220, 2020). "Taken together, our data suggest that TRPM7/RPSA complex regulated human pancreatic cancer cell migration." (PMID 32733880, 2020). "The overexpression of TRPM7 protein in pancreatic cancer was further confirmed, and a correlation was found between TRPM7 expression levels and the size and stage of tumors." (PMID 32182937, 2020). "Pancreatic cancer cell lines also exhibit elevated levels of TRPM7 whose silencing decreases their invasive capacity." (PMID 31275168, 2019).
pancreatic cancer (continued). "TRPM7 protein expression correlates with primary tumor size and stage of malignant pancreatic tumors, and is expressed at higher levels in metastatic tumors and in primary metastasizing tumors than normal tissue." (PMID 31275168, 2019). "For each histological type of pancreatic tumors, the proportions of samples with corresponding TRPM7 expression levels have been reported." (PMID 28379203, 2017). "The mechanisms that mediate the various cellular effects of TRPM7 in pancreatic cancer remain to be determined." (PMID 25770184, 2015). "In this study, we aim to determine the significance of TRPM7 in pancreatic cancer by immunohistochemical analysis of its expression in pancreatic tissues and examine the role of TRPM7 in cancer cell invasion." (PMID 25770184, 2015). "The positive correlation between TRPM7 expression in pancreatic adenocarcinoma and the tumor size and metastasis is consistent with the functional roles of TRPM7 in pancreatic cancer cells." (PMID 25770184, 2015). "Taken together, the current data and our previous findings suggest an important role of TRPM7 ion channels in mediating the growth and metastasis of pancreatic cancer." (PMID 25770184, 2015). "To further understand the significance of the aberrantly over-expressed TRPM7 in pancreatic cancer, we investigated the role of TRPM7 in cell invasion by reducing its expression." (PMID 25770184, 2015). "Our previous studies in zebrafish development have led to identification of the novel roles of the transient receptor potential melastatin-subfamily member 7 (TRPM7) ion channels in human pancreatic cancer." (PMID 25770184, 2015). "We also investigated the role of TRPM7 channels in pancreatic cancer cell invasion using the MatrigelTM-coated transwell assay." (PMID 25770184, 2015). "The results indicate that TRPM7 is aberrantly over-expressed in pre-malignant tissues and in various types of pancreatic neoplasms." (PMID 25770184, 2015). "In conclusion, expression of TRPM7 is cell-type specific in adult human pancreatic tissues, and the TRPM7 ion channels are aberrantly expressed in various types of pancreatic neoplasms." (PMID 25770184, 2015). "In this study, we provide evidence that TRPM7 is variably expressed in different types of pancreatic tumors and aberrantly over-expressed in most of the 282 cases of pancreatic adenocarcinoma examined." (PMID 25770184, 2015). "TRPM7-mediated cellular proliferation of exocrine pancreatic epithelia in zebrafish larvae and in human pancreatic cancer is Mg2+-dependent." (PMID 25079291, 2014). "This is supported by the evidence that small interfering RNA directed against TRPM7 enhances cytotoxicity in pancreatic cancer cells when combined with the chemotherapeutic drug." (PMID 25079291, 2014). "The pancreatic cancer cells with silenced expression of TRPM7 exhibit morphological features including enlarged cell size and multiple nuclei, suggestive of replicative senescence." (PMID 24278689, 2012). "With the goal of identifying and developing clinical biomarkers and therapeutic targets in pancreatic cancer, we are actively investigating the mechanistic roles of TRPM7 and TRPM8 ion channels in the initiation, growth, and invasion of pancreatic neoplasia." (PMID 24278689, 2012). "By using small interfering RNA (siRNA) to inhibit translation of TRPM7 mRNA in the pancreatic cancer cells, we provide evidence that TRPM7 is required for cellular proliferation by preventing cell cycle arrest in the G0/G1 phases." (PMID 24278689, 2012). "Combining anti-TRPM7 siRNA and gemcitabine improved cytotoxicity, suggesting that modulation of TRPM7 expression could improve treatment response in pancreatic cancer when combined with apoptosis-inducing agents." (PMID 37189782, 2023). "Knockdown of the genes encoding TRPM7 and TRPM8 induces senescence in pancreatic cancer cells." (PMID 35406743, 2022). "In pancreatic cancer, TRPM7 is highly expressed, correlating to tumor size and stage." (PMID 36363540, 2022).